CDKN1A (cyclin dependent kinase inhibitor 1A)
Diseases named in the same sentence as CDKN1A in open-access papers (continued):
Sharing a sentence is not in itself a finding about the gene and the disease.
melanoma (continued). "As a confirmation of this, the expression of CDKN1A gene codifying for the CDK inhibitor p21 is about 20 times higher in treated melanoma cells (FC = 19.35)." (PMID 23642048, 2013). "Therefore, we determined the expression of CCND1 and CDKN1A mRNAs in melanoma cells treated with 20, 40, and 60 μM." (PMID 36674631, 2023). "All these suggest that CDKN1A can be used as a tumor suppressor gene in melanoma." (PMID 38070141, 2023). "Interestingly, inhibition of ROCK (using Y27632), a downstream target of RHOA signalling, also induces CDKN1A in melanoma, and ROCK1 has been identified as a potential candidate for combinatorial therapy with BRAF inhibitors." (PMID 27835901, 2016). "We hypothesised therefore that melanoma cells can utilise either CDKN1A/P21 or CDKN1C/P57 to mediate cell cycle arrest induced by MITF and this is reflected in the expression levels of the alternate CDK inhibitors in different melanoma cell lines." (PMID 25755924, 2015). "We identified by mass spectrometry phosphorylation of Ser78 in endogenous CDKN1A upon UVB irradiation in mouse melanoma cells, Phosphorylation on Ser78 was significantly decreased in LKB1 depleted cells (30% vs. 1% of peptide phosphorylated respectively; p<0.0001)." (PMID 25329316, 2014). "Again, this molecular response in fibroblasts is weaker than that in melanoma cells (CDKN1A FC = 4.29), without causing in normal cells block of proliferation or cell death." (PMID 23642048, 2013). "Because low-dose Aza induced CDKN1A in several melanoma cell strains in which the promoter was unmethylated, we attempted to identify additional genes that behave in a similar fashion whose reactivation can lead to growth arrest and further explored the mechanism of Aza activity." (PMID 19234609, 2009). "The increase in the transcriptional activity of the CDKN1A gene in both amelanotic and melanotic melanoma cells under the influence of pterostilbene may result in cell cycle arrest and a decrease in the proliferation potential of melanoma cells." (PMID 36674631, 2023). "Knockdown of CDKN1A could promote melanoma proliferation in the G1 cell cycle." (PMID 36338999, 2022). "We then validated the transcriptional expression of key candidate genes such as CDKN1A (P21), GADD45A, and MCM3 after this compound treatment and knocking down Fyn expression in melanoma cells." (PMID 32565740, 2020).
melanoma (continued). "Consistent with the sequencing results, RT-PCR confirmed that GADD45A and CDKN1A were upregulated in the Lj-1-60-treated group, while minichromosome maintenance 3 (MCM3) was downregulated in melanoma cells Sk-Mel-5 and Sk-Mel-28." (PMID 32565740, 2020). "In our experiments, the increased nuclear localization of CDKN1A and CDKN1B in both melanoma cell lines after TSPC treatment supports the antitumor activity of this compound." (PMID 28231799, 2017). "Furthermore, 4 melanoma pathway genes (CDKN1A, CDKN2A, CXCR4 and RAD51) were also expressed differently in normal tissues compared with melanoma." (PMID 38070141, 2023). "Focal adhesion kinase‐integrin β1 signaling regulates CDKN1A and CDKN1B expression in disseminated cancer cells, and is essential In the present study, human melanoma cells treated with intermediate doses of dacarbazine showed similar alterations of cell distributions in different cell cycle phases." (PMID 36533319, 2023). "Furthermore, CDKN1A, CDKN2A, CXCR4 and RAD51 in the melanoma pathway, were also differentially expressed between normal skin and melanoma." (PMID 38070141, 2023). "However, STX140 (100 nM) significantly (p < 0.05) increased CDKN1A and GADD45A expression in resistant melanoma cells." (PMID 37511073, 2023). "In addition to several ECM proteins that were found to be downregulated we also observed upregulation of several pro-apoptotic genes such as BAX, CDKN1A, GADD45A, GADD45B, etc. in TP-472–treated melanoma cells." (PMID 34771678, 2021). "In mouse melanoma cells Rb1 cooperates with MITF to activate expression of Tyr and Cdkn1a/p21Cip1." (PMID 32850962, 2020). "Histone hypoacetylation is also involved in the progression of melanoma cells since the reversible deacetylation by histone deacetylases (HDAC) can down-regulate several onco-suppressor genes, such as CDKN1A and phosphatidylinositol-4,5-biphosphate 5-phosphatase A (PIB5PA)." (PMID 31861757, 2019). "A low incidence of mutations has been described for the CDKN2B gene in sporadic melanoma tumors; however, no structural defects have been detected in the CDKN1A gene in human melanoma." (PMID 15819981, 2005). "Meanwhile, it was confirmed that in melanoma, CDKN1A and CDKN2A could not affect the miR-300 transcription and maturation process." (PMID 38070141, 2023). "Moreover, miR-221 targets are the E2F transcription factor 1 (E2F1), the phosphatase and tensin homolog (PTEN) and the cyclin-dependent kinase inhibitor 1 (CDKN1A), all belonging to critical cancer related pathways in HCC as well as other types of cancer including melanoma." (PMID 31906510, 2020). "However, CDKN1A and CDKN2A expression differences have not been found in different subtypes of melanoma, suggesting that CDKN1A and CDKN2A may become new type markers." (PMID 38070141, 2023). "Furthermore, WIPI1 was a relevant novel melanoma marker, and the increased expression of WIPI1 indicated poor clinical outcome in uveal melanoma In osteosarcoma, WIPI1 expression was obviously elevated, which promoted the proliferation of osteosarcoma cells through regulating CDKN1A expression." (PMID 34335109, 2021). "A negative correlation between CDKN1A and CDKN2A was found, especially in primary melanoma." (PMID 38070141, 2023).
melanoma (continued). "In our melanoma model, the expression of these genes is increased in the tumor cell lines and, as hypothesized, there was a significant reduction of Cdkn1a, Bcl2 and Psen2 expression in SIRT1-silenced 4C11+ melanoma cell line (respectively) compared to non-silenced cell lines." (PMID 29383100, 2017).
colorectal cancer (74 papers, 1999 to 2025). A primary or metastatic malignant neoplasm that affects the colon or rectum. "More importantly, cancer cell lines with lower expression levels of CDKN1A showed greater sensitivity to M1 virus than those with higher levels, and the deficiency of CDKN1A is a ubiquitous event in colorectal cancer patients." (PMID 33037696, 2020). "Both the database and our experiments strongly suggest that the expression of CDKN1A was frequently deficient in colorectal cancers, which implies the application of M1 virus." (PMID 33037696, 2020). "Studies from Liu et at showed that CBX3 was over-expressed in human colorectal cancer and it promoted cell proliferation of colorectal cancer cell lines by directly regulating CDKN1A in a manner associated with methylation of histone H3K9 on its promoter." (PMID 30481161, 2018). "CBX3 expression was increased in human colorectal cancer and promoted in vitro and in vivo proliferation of the tumor cells, which was associated with its regulation on CDKN1A in colorectal cancer cells." (PMID 29903985, 2018). "CDKN1A serves as a tumor suppressor and is deficient in various cancer types in addition to colorectal carcinoma, which indicates that CDKN1A expression may serve as an M1 virus biomarker in pan‐cancer types." (PMID 33037696, 2020). "Several reports indicate that CDKN1A, which is also associated with increased risk of esophageal cancer and colorectal cancer, may be a useful predictor and target for cancer treatments involving cell cycle alteration." (PMID 27765935, 2016). "Our results suggest that TFAM-induced changes of the mitochondrial genome lead to upregulated CDKN1A/p21 expression in colorectal cancer cells identifying p21 as a new possible linker between mitochondria and nucleus." (PMID 39580766, 2024). "It was also found that miR-520g mediated the resistance of colorectal cancer cells to 5-fluorouracil (5-FU) or oxaliplatin by downregulating CDKN1A expression." (PMID 36765397, 2023). "Here we also show that SPUD can be detected in HCT116 colorectal carcinoma, a cell line historically used to study CDKN1A transcriptional regulation, and in keratinocytes." (PMID 37870464, 2023). "Recent evidence from studies has shown that CBX3 is upregulated in colorectal cancer in human, which stimulated cell proliferation by candidly modulating CDKN1A through methylation of histone H3K9 at its promoter." (PMID 35573019, 2022). "In summary, we found that MSTO2P was upregulated in CRC and promoted colorectal cancer progression through epigenetically silencing CDKN1A mediated by EZH2." (PMID 35346226, 2022). "LncRNA MSTO2P promoted colorectal cancer progression through epigenetically silencing CDKN1A mediated by EZH2." (PMID 35346226, 2022). "This was especially surprising as previous reports indicated altered levels of p21/CDKN1A in colorectal cancers, although the changes in CDKN1A expressions between CRC and gastric cancers were not consistent." (PMID 35681633, 2022). "Long non-coding RNA CRNDE promotes the proliferation of colorectal cancer cells through epigenetic silencing of CDKN1A expression." (PMID 33537240, 2020). "The correlation of NDRG1 and CDKN1A was analyzed in three colorectal cancer datasets (GSE33114, GSE4107, and TCGA)." (PMID 31831018, 2019). "Recent studies show that CBX3/HP1γ is upregulated in human colorectal cancer and that it promotes cell proliferation by directly regulating CDKN1A via methylation of histone H3K9 on its promoter." (PMID 31375643, 2019). "The present results suggest that the genetic variants of the CDKN1A (rs1321311) and RHPN2 (rs10411210) genes can be used as prognostic biomarkers for patients with surgically resected colorectal cancer." (PMID 25799222, 2015).
colorectal cancer (continued). "In addition, loss of CDKN1A/p21 is associated with CMS4 colorectal cancer, an aggressive form of colorectal cancer characterised by the presence of mesenchymal-type cells." (PMID 38139316, 2023). "Additionally, multiple lines of evidence have demonstrated that MYC can suppress the expression of CDKN1A in cancer like colorectal cancer." (PMID 26083494, 2015). "In mouse pluripotent and human colorectal cancer cells, SRSF3 binding enhances the processing of two paralog miRNAs, miR‐17 and miR‐20, that control cell cycle and proliferation through CDKN1A/p21." (PMID 37306233, 2023). "For instance, HIF1A displaces MYC binding from the promoter of cyclin-dependent kinase inhibitor 1A (CDKN1A, p21cip1) and upregulates the expression of p21 (CDKN1A) in human HCT116 colorectal carcinoma cell line." (PMID 37998757, 2023). "LncRNA CRNDE promotes colorectal cancer cell proliferation by inhibiting the expression of DUSP5 and CDKN1A." (PMID 33522895, 2021). "In other study, the supplementation of pomegranate extract in patients with colorectal cancer had a significant down-regulating effect on the expression of colorectal cancer-related genes such as CD44, CTNNB1, CDKN1A, and EGFR in surgical colon samples." (PMID 33322700, 2020). "Therefore, we detected the protein expression of CDKN1A in pancreatic carcinoma and colorectal carcinoma cell lines, which have been reported to frequently harbor K‐RAS mutations, and analyzed the correlation between the cell‐killing effect of M1 virus and CDKN1A expression." (PMID 33037696, 2020). "Expression of CDKN1A, which was previously shown to increase with 5-AzaC treatment and of CDKN2A, a gene known to be frequently methylated in colorectal cancers, were used as positive controls and showed increased transcription in most cell lines." (PMID 21079778, 2010). "MKI67 and PCNA were used as positive markers, and CDKN1A was used as a negative marker for cell proliferation in colorectal cancer." (PMID 34548081, 2021). "Additionally, the effect of mature miR-34 mimics on NR4A2 expression was assessed in another colorectal cancer cell line, RKO, with similar results observed on CDKN1A and NR4A2 expression." (PMID 27121375, 2016). "The finding that ATF6 silencing inhibits cell-cycle progression and increases CDKi expression in colorectal cancer cells is consistent with recent evidence that ATF6 deletion in pancreatic β-cells during insulitis leads to cell-cycle arrest and increases the expression of CDKN1A." (PMID 39324706, 2024). "Our results showed the negative expression of the cell cycle regulator CDKN1A and WNT signalling pathway regulator APC in a subset of the CTCs, suggesting the involvement of the canonical WNT pathway in colorectal carcinoma." (PMID 33092235, 2020).
lung carcinoma (74 papers, 2009 to 2026). "The 8 FRGs (ACSL3, FADS2, GLS2, HSF1, PANX1, PHKG2, VDAC2, and CDKN1A) that we selected to be associated with the diagnosis and prognosis of lung cancer have been shown to play important roles in cancer and tumor immunity." (PMID 38743344, 2024). "The inhibition of cell cycle progression was found to be associated with a higher expression in the levels of CDKN1A expression in lung cancer cell line." (PMID 36500446, 2022). "High expression of HSP90AA1, RAC1 and CDKN1A was significantly associated with a lower rate of overall survival in lung cancers." (PMID 32457348, 2020). "RUNX1T1 interacts with the CDKN1A (p21) promoter and is associated with reduced histone H3 acetylation, resulting in decreased p21 expression and increased E2F transcriptional activity in lung cancer cell lines." (PMID 33084222, 2021). "Thus, we suggest that dysregulation of EHMT1 is clearly associated with lung cancer proliferation via regulation of CDKN1A." (PMID 34214254, 2021). "An earlier study on human lung carcinoma cells (in vitro and in vivo) has demonstrated that overexpressed Brachyury divides at slower rates than those with low-expressed Brachyury, a phenomenon associated with marked downregulation of cyclin D1, phosphorylated Rb, and CDKN1A (p21)." (PMID 25499255, 2014). "The findings established that the mRNA expressions of CDKN2A and CDKN1A were significantly elevated in lung cancer cells treated with H2O2, and β-galactosidase staining was more intense." (PMID 39769336, 2024). "Our findings suggest a potential involvement of SNAP25-AS1, RP11-58O9.2, TENM4, XRCC2, LINC01164, VLDLR-AS1, RP11-14I17.2, and CDKN1A in the development of hypoxia-induced lung cancer." (PMID 39236027, 2024). "Through the bioinformatics analysis (DEG analysis and GO and KEGG pathway enrichment analysis) of disease signature, we found that CDKN1A, a cell cycle regulator, is up-regulated, and the cell cycle pathway is enhanced in lung cancer patients." (PMID 38994794, 2024). "Fentanyl inhibits lung cancer viability and invasion via repression of HDAC5 CDKN1A upregulation and cisplatin‐pemetrexed resistance in non‐small cell lung cancer cells." (PMID 39236027, 2024). "Here, we found that Gsk3b, Notch2, Pik3cb, Myc, Cdkn1a, and Smad3 were increased in human lung cancer tissue and Cd‐transformed cells, while Pik3cb, Myc, Cdkn1a, and Smad3 were negatively correlated with circCIMT." (PMID 36814305, 2023). "It has been reported that knocking out CDKN1A enhances the sensitivity of A549 cells (lung cancer cells) to doxorubicin-induced ferroptosis, suggesting that CDKN1A inhibits ferroptosis." (PMID 38002949, 2023). "ZEB proteins have been shown to protect lung cancer cells from EGFR-induced senescence through their ability to down-regulate CDKN1A and CDKN2B." (PMID 38069026, 2023). "Studies have shown that miR-33b-3p can promote the survival and cisplatin resistance of A549 human lung cancer cells by targeting CDKN1A after DNA damage." (PMID 36765397, 2023). "The Kaplan–Meier plotter was used for univariate analysis of survival time according to CDKN1A expression in lung cancer, lung adenocarcinoma, and squamous cell carcinoma patients." (PMID 36054146, 2022). "Based on mRNA levels, patients with lung cancer and lung adenocarcinoma with high CDKN1A expression showed significantly poorer overall survival compared to those with low CDKN1A expression." (PMID 36054146, 2022). "To investigate the effect of both CDKN1A in PC9 and TIMP3 in A549 on cell proliferation in ALKBH5-deficient lung cancer cell lines, we confirmed the reduced expression using siRNA." (PMID 35318440, 2022). "The results of the current study indicate that CDKN1A expression is epigenetically controlled by EHMT1 expression in lung cancer." (PMID 34214254, 2021). "Curcumin treatment upregulated CDKN1A in PCa and lung cancer cells, resulting in the induction of cell cycle arrest and apoptosis." (PMID 34366863, 2021).